H2AX (H2A.X variant histone)
Diseases named in the same sentence as H2AX in open-access papers (continued):
Sharing a sentence is not in itself a finding about the gene and the disease.
tumor (continued). "We then analyzed tumors from each group by flow cytometry, measuring phospho-γ-H2AX activation as a marker for DNA damage, a key measure of tumor cisplatin exposure." (PMID 39671496, 2024). "The protein expressions of GSN, casepase‐3 and γ‐H2AX were measured in the xenograft tumours after RT." (PMID 38803199, 2024). "Patients exhibiting high levels of γ-H2AX expression experience more frequent R1 resections, indicating advanced tumor stages in this subgroup." (PMID 38502354, 2024). "Remarkably, the ATMi AZD0156, but not the ATRi AZD6738, robustly restored fork degradation in BRCA- H2AX-deficient cells, indicating that the ATR signalling branch is dispensable for fork protection in these tumours." (PMID 38789420, 2024). "Our research revealed that PARP and DNA-PK are activated upon binding to AsiDNATM in normal and tumour cells, assessed by PARylation and phosphorylation of H2AX, respectively (this study, see also)." (PMID 38476631, 2024). "Animal experiments revealed an increase in γ‐H2AX expression in tumor tissues isolated from KO mice compared with those from the NC group." (PMID 39555714, 2024). "Compared to the sample taken before chemotherapy, we found a clear H2AX reduction in tumour cells of the drug-resistant colon metastasis." (PMID 38789420, 2024). "Consistent with reduced tumor size the combination treatment also showed higher expression of DNA damage markers (gamma-H2AX and RPA32) and reduced levels of the proliferation marker Ki67." (PMID 39528654, 2024). "We studied the time-course levels of total and phosphorylated histone H2AX (Ser139), an established indicator of DNA DSBs, in the non-tumor thyroid cell line (HThy-ori-3.1) post-5 Gy X-ray irradiation." (PMID 39047147, 2024). "In contrast, cisplatin-treated NPEPPS−/−(WT-FLAG) tumor cells exhibited lower levels of phospho-γ-H2AX, indicative of reduced exposure and sensitivity to cisplatin." (PMID 39671496, 2024). "To study the effect of SLpFlaB and RT on tumor cells, we detected the expression of γ-H2AX and cleaved caspase-3." (PMID 37515090, 2023). "H2AX phosphorylation has been shown to mediate apoptosis and its inhibition has been shown to correlate with tumor resistance to radio-and chemotherapies." (PMID 36831129, 2023). "More importantly, the increase of γ‐H2AX expression in tumor further support TI17‐induced DNA damage responses." (PMID 37942576, 2023). "To confirm the DNA damage in tumor tissues, we analyzed the levels of r-H2AX and apoptosis in the tumor mass through an IHC and Tunel assay." (PMID 37296596, 2023). "Knockdown of PRDX1 attenuated the up-regulation of GADD45G and γ-H2AX with Celastrol or compound 19-048 treatment, which is consistent with the efficacy assessment for tumor volume and weight." (PMID 36732502, 2023). "In our work, the number of γ-H2AX foci in tumor cells and the ratio of apoptotic cells rose following 4 Gy X-ray irradiation, leading to an increase in the cell’s radiosensitivity." (PMID 37759607, 2023). "The CR cell lines also maintained the characteristics of tumor radiosensitivity in vitro, for more double-strand breaks and γ-H2AX foci shown in radiosensitive CR cell lines compared with radioresistant ones after irradiation." (PMID 36867313, 2023). "The tumors overexpressing DDUP/WT exhibited higher resistance to carboplatin treatment, as indicated by the increased tumor volume, higher Ki-67 index, and decreased γ-H2AX and TUNEL signals." (PMID 37633920, 2023). "Compound 4g also activated the LC3 signaling pathway to induce autophagy in tumor cells, and activated the γ-H2AX signaling pathway to induce DNA damage in tumor cells." (PMID 37608893, 2023). "Phosphorylated H2AX has been shown to promote DNA repair and play a role in genome stability, cell cycle checkpoint response, and tumor suppression." (PMID 37049894, 2023).
tumor (continued). "Rhamm−/− tumor cells exposed to H2O2 or Cisplatin contain more DNA damage than Wildtype tumor cells, as detected by gamma H2AX staining." (PMID 37349798, 2023). "These combinations resulted in increased DNA DSBs, as assessed by γ-H2AX foci formation, and significantly enhanced the in vivo anti-tumor efficacy." (PMID 38140100, 2023). "In tumor models, the number of γ-H2AX foci observed after quantification increased with BRD expression as well as with the therapeutic dose of radioiodine therapy in vivo." (PMID 36769088, 2023). "Tumor viability reduction was similar in both single-agent dasatinib and combination treatment groups, and phosphorylation of H2AX was significantly higher in the tumors treated with dasatinib." (PMID 35655525, 2022). "The γ-H2AX staining results reflect the findings of treatment response measured by tumor volume; M3814 + IR had significantly increased DNA damage compared with vehicle alone (p < 0.01)." (PMID 35046420, 2022). "Sections from PC showed γ-H2AX-positive staining, however liver metastases and primary tumor sections were also positive for this marker, although to a lesser extent." (PMID 35844581, 2022). "Compared to other groups, mice in the ch-K5(s-s)R8-An/(Dbait-DOX) micelles + RT group exhibited a higher extent of nuclear pyknosis and liquefactive necrosis, with an increased γ-H2AX level in orthotopic tumor sections." (PMID 35975300, 2022). "PARP transcripts (qPCR) and PARP1, H2AX and gammaH2AX protein (RPPA) levels were compared in control liver vs HBV-, HCV-, alcohol- and NASH-associated HCC (Tumor/Peri-Tumor) tissues." (PMID 35804458, 2022). "Consistently, the higher signal of green fluorescence corresponding to γ-H2AX is observed in the tumour tissues of mice treated with NMPNs as compared with that of mice treated with cisplatin or PNPs." (PMID 36450764, 2022). "Using immunoblot analysis, we found that the levels of γ-H2AX were higher in tumor samples derived from hTS/Men1–/– compared with Men1–/– mice." (PMID 36048542, 2022). "Evidence suggests that tumor cells exposed to DSB-inducing agents are more likely to die within 24 h of treatment if they retain microscopically visible γ-H2AX foci." (PMID 36142803, 2022). "As expected, MUS81 knockdown tumor cells showed higher expression of γ-H2AX than control cells in response to talazoparib." (PMID 35480096, 2022). "Combination treatment led to more DNA double strand breaks (phospho-H2AX positive cells), less proliferative and more apoptotic tumour cells than in irinotecan-treated LS-1034 tumours 72 h after treatment start." (PMID 35197630, 2022). "Our results showed that depletion of TAMs significantly increased the amount of cytosolic dsDNA and γ-H2AX in tumor cells upon olaparib treatment." (PMID 35641483, 2022). "IHC was consistent with previous results; CPX decreased Ki-67 staining (a cell proliferation marker) and increased p-H2AX and Tunnel (apoptosis marker) staining in tumor tissue." (PMID 35251970, 2022). "Ex vivo analysis of brain cryo-sections showed that tumor tissues in both treatment groups displayed a higher level of phospho-H2AX (p-H2AX), indicating greater DNA damage in the treatment groups compared to the control." (PMID 35565337, 2022). "Tumor sections were stained for γ-H2AX, a marker of cell death, which was observed in HAdV-D10.A20-treated tumors but not in HAdV-D10- or PBS-treated tumors." (PMID 35399606, 2022). "It has been shown that, in untreated normal and tumor cells, a fraction of the histone H2AX remain phosphorylated and the extent of this constitutive H2AX phosphorylation depends on cell type and cell-cycle phase." (PMID 36551689, 2022). "Third, we assessed histological tissue damage and γ-H2AX immunofluorescence in tumor biopsies after the completion of therapeutic regimens." (PMID 35975300, 2022). "Within the tumours, the nuclear β-catenin corresponded with sites of double-strand DNA breaks, as indicated by phospho-γ-H2AX staining." (PMID 34916592, 2022).
tumor (continued). "Then the proteins were extracted from mouse tumours and the γ‐H2AX expression was tested by western blot assay." (PMID 35187743, 2022). "As expected, tumor tissues from the BTP-7-CPT group had a higher level of p-H2AX than the Scr-7-CPT group, underscoring the ability of BTP-7 to improve drug targeting to GBM." (PMID 35565337, 2022). "Compared with the other agents, RT+AL-HA-Tyr decreased HIF-1α, Ki67, and VEGF-A expression, and increased γ-H2AX levels in tumor cells." (PMID 33777779, 2021). "Subsequently, we quantified the percentage of γ-H2AX positive and apoptotic areas within the tumor regions." (PMID 33490949, 2021). "We verified the increased RNA expression of MMEJ-related H2ax, Fen1, Cdk1, Plk1, and Polθ and decreased RNA expression of Mdc1 in the MmuPV1 tumor tissues by real-time RT-qPCR." (PMID 34343212, 2021). "In vitro and in vivo experiments demonstrated that suppressing CD81 by siRNA/shRNA enhanced radiation-induced cell killing and DNA damage of γ-H2AX formation, and delayed tumor xenograft growth of GBM." (PMID 33919192, 2021). "In agreement, the results of Western blotting in tumor tissues showed that expression levels of γ-H2AX, p-ATR, RPA32, CHK1, and RAD51 were upregulated, and the phosphorylation level of CHK1 (p-chk1) was downregulated." (PMID 34660289, 2021). "To exclude signaling effects as the cause of the phosphorylation of H2AX, we confirmed these results by COMET assay again showing almost no DNA damage at active concentrations of mithramycin in rhabdoid tumor cells (Fig EV1A)." (PMID 33332735, 2021). "NO.0449-0145 treatment increased the positive staining for γ-H2AX and 53BP1 in tumor tissues and impaired the expression of Ki67, which is a known marker of cell proliferation." (PMID 34006852, 2021). "Cell cultivation in PAM also led to H2AX histone phosphorylation These experiments were performed on HCT116 colorectal multi-cellular tumour spheroids." (PMID 34830132, 2021). "Immunohistochemical analysis of tumor tissues indicated that the combination obviously reduced expression of HR repair molecules and increased the DNA damage biomarker γ-H2AX, consistent with the in vitro results." (PMID 34039959, 2021). "Of note, the degrees of H2AX phosphorylation and apoptosis varied between different cells of the same tumor upon treatment with the drug combination." (PMID 34944784, 2021). "IHC and Western blotting in tumor tissues showed that expression levels of γ-H2AX, p-ATR, RPA32, CHK1, and RAD51 were upregulated, and the phosphorylation level of CHK1 (p-chk1) was downregulated." (PMID 34660289, 2021). "Consistently, there was a significant decrease in BRCA1 protein level and increase in γ-H2AX level in the GSK3β KO tumor xenografts treated with simmiparib." (PMID 33589588, 2021). "It should also be noted that many of the studies that describe HDACi-induced delayed γ-H2AX foci repair kinetics report results from human tumor cell lines." (PMID 34513712, 2021). "RT+AL-HA-Tyr more significantly reduced 18F-FMISO uptake as well as HIF-1α, Ki67, and VEGF-A expression, and increased γ-H2AX expression in tumor cells compared to the other treatments." (PMID 33777779, 2021). "Significantly more cells were positive for γ-H2AX in tumor tissues of the RT + AL-HA-Tyr, than the RT and control groups (65.3 ± 2.4% vs. 52.5 ± 1.9% and 5.2 ± 0.9%; p < 0.01, p < 0.001, respectively)." (PMID 33777779, 2021). "The expressions of these genes are significantly different between the tumor groups and the normal groups, except for H2AX." (PMID 35095717, 2021). "Treatment with BIBR1532 increased γ-H2AX foci generation much more strongly in CD133+ CSCs than in bulk tumor cells, indicating a preferential induction of DNA damage after telomerase inhibition in CSCs." (PMID 34201898, 2021).
tumor (continued). "Highly γ-H2AX positive cells were mainly found within the vital tumor areas and their direct surroundings, which also coincided with our planned volume as revealed by the comparison of planning target volume (PTV) and γ-H2AX immunostaining patterns." (PMID 34298631, 2021). "Further examination on the expression of γ-H2AX in tumor cell nuclei demonstrated that the combination of S4 with radiotherapy exaggerated DNA damage in ESCC xenograft compared to the groups treated with S4 or X-ray irradiation alone." (PMID 34249682, 2021). "Compared to vehicle control and monotherapy groups, the combined treatment reduced tumor cell proliferation, while increased DNA damage response, as assessed by Ki-67 staining and γ-H2AX staining." (PMID 34162828, 2021). "Biochemical analyses of the tumor samples confirmed that PARPi treatment increased DNA damage accumulation, and decreased cell proliferation, as judged by γ-H2AX and phospho-histone H3, respectively." (PMID 35071239, 2021). "We also showed that RT + AL-HA-Tyr significantly increased the expression of γ-H2AX and decreased that of Ki67, indicating positive anti-tumor effects." (PMID 33777779, 2021). "γ-H2AX foci form to various extents in tumour cell lines, and generally follow the typical post-irradiation kinetics." (PMID 34094987, 2021). "As DNA damage repair is recognized as a vital mechanism in tumor radioresistance and γ-H2AX was regarded as a marker of DNA damage, we detected the levels of γ-H2AX in U251, U251R, and T98G cells exposed to 6 Gy X-rays irradiation." (PMID 33919192, 2021). "Compared to the either therapies alone and to the untreated controls, the thermo-chemotherapeutic tumor treatment led to a substantial overexpression of H2AX and phospho-H2AX (indicators of DNA replication stress and DNA repair processes, respectively)." (PMID 32916798, 2020). "The majority of phospho-H2AX staining was observed in the areas of tumor in six different tumor samples." (PMID 32934779, 2020). "Tumor expression of pRPA (P = 0.686) and γ-H2AX (P = 0.798) were not statistically different between the AR+ vs. AR− TNBC cases." (PMID 32964114, 2020). "WB data also revealed a substantial increase of γ-H2AX-expression in all tumor cell lines treated with combination of Dox and MK-2206 when compared to the cells treated with Dox alone." (PMID 33266502, 2020). "In LC-COPD patients, the percentage of γ-H2AX positive cells, a marker of DNA damage, was significantly higher in the tumors compared to non-tumor lung samples." (PMID 33187221, 2020). "Treated lungs showed a significantly elevated level of γ-H2AX expression in tumor cells compared to the sham-treated control." (PMID 33371498, 2020). "Unrepairable DNA damage in Dox-treated tumor cells cultured in presence of AKT inhibitor was also confirmed by quantitative analysis of γ-H2AX-expression, a well-known marker of the DNA DSBs." (PMID 33266502, 2020). "Consistent with equivalent tumor cytotoxicity, we observed similar γ-H2AX positive foci in TROMA-1 positive ID8 cancer cells in the omentum of mice at 4, 12 and 24 h following FLASH and CONV irradiation." (PMID 33303827, 2020). "Non-treated GIST T-1R cells exhibited a low level of γ-H2AX/Rad51 foci, whereas vast majority of tumor cells became γ-H2AX/Rad51-foci positive after Dox treatment." (PMID 33266502, 2020). "In the present study, tumor cells that underwent circulation, confinement and constrictions indeed were found to present increased levels of DNA damage marker, γ-H2AX." (PMID 32286431, 2020). "As the pan-nuclear γ-H2AX pattern is easily distinguishable from the focal γ-H2AX pattern, the pan-nuclear γ-H2AX pattern will be extremely useful to determine the efficacy of chemotherapeutic drug combinations to kill tumor cells in translational studies." (PMID 30871194, 2019).
tumor (continued). "In contrast, the levels of cleaved caspase-3, 53BP1, and γ-H2AX were upregulated in tumor cells treated with RT + BEZ235 + mBEZ235 when compared with those treated with RT + BEZ235." (PMID 31430901, 2019). "DNA double strand‐breaks indicated by the increased intensity and granularity of the γ‐H2AX immunoreaction in tumor cell nuclei, was also detected at high levels both after mEHT monotherapy and after combined mEHT + Dox therapy compared to controls." (PMID 31183995, 2019). "We also show increased levels of γ-H2AX staining at 15 Gy, confirming radiation-induced DNA damage has occurred in the tumours." (PMID 31109312, 2019). "At 3 and 10 days, unirradiated tumours were found to have increased levels of γ-H2AX compared to irradiated tumours (p < 0.0001 day 3, p = 0.001 day 10)." (PMID 31109312, 2019). "A previous study showed that cyclin D1 depletion caused DNA damage via modulation of γ-H2AX and PARP and re-sensitized tumor cells to antitumor drug." (PMID 30326563, 2018). "In our study, we evaluated the expression of histone H2AX phosphorylation by immunohistochemistry in mouse tumor tissue following different methods of treatment." (PMID 29416613, 2018). "Binding of Bclaf1 to H2AX activated the tumor suppressing effects of Bclaf1, thus inducing cell death." (PMID 29795334, 2018). "In vivo, the combination of oridonin and radiation effectively inhibited H460 xenograft tumor growth, with higher caspase-3 activation and H2A histone family member X (H2AX) phosphorylation compared with that of radiation alone." (PMID 30104472, 2018). "The results showed that CDDP increased the γ-H2AX expression in all tumour cells, thus implying similar DNA damage." (PMID 29449532, 2018). "Sustained γ-H2AX induction (>24 h) usually indicates inability to repair extensive DNA damage induced by ionising agents and was suggested to be a predictor of tumour radiosensitivity and cytotoxicity." (PMID 29784888, 2018). "Our results are consistent with this finding as we showed that remaining tumor cells after radiation has a higher sustained level of DNA damage with an elevated γ-H2AX." (PMID 29859114, 2018). "As expected, depletion of the NADPH oxidases attenuated DNA damage, as reflected by γ-H2AX, in tumor xenografts formed by A2780-shPARP1 cells." (PMID 29684820, 2018). "Higher cryptogenic level of γ-H2AX in tumor cells is attributed to dysfunctional telomeres that drives genomic instability." (PMID 29859114, 2018). "It has been recently reported that prolonged exposition to irinotecan determined, in certain tumor cell lines, the up-regulation of γ-H2AX and phospho-Chk2, two DNA damage signal proteins able to enhance DNA repair thus reducing chemotherapy activity." (PMID 29416820, 2018). "Haploinsufficiency of tumor suppressor, such as H2AX, Tip60 and BubR1, have also been reported to involve in genomic instability and accelerated tumorigenesis through direct or indirect participation in DNA damage repair." (PMID 28422719, 2017). "Together, we propose that PKM2 promotes genomic instability in tumor cells which involves direct phosphorylation of H2AX." (PMID 29312595, 2017). "BSI-201, by activating gamma-H2AX, induces cell cycle arrest in the G2/M phase in tumor cell lines, and potentiates the cell cycle effects of DNA damaging modalities in tumor cell lines." (PMID 29214032, 2017). "Mice were sacrificed within 24 hours of treatment, and tumor tissue was analyzed for levels of γ-H2AX, first by using the well-established IFA." (PMID 28158293, 2017). "Pairing γ-H2AX analysis and apoptosis assays in human tumor cell lines was predictive of their radiosensitivity in a standard colony-forming assay." (PMID 29077012, 2017).